TFF1 (trefoil factor 1)
Description:
Stabilizer of the mucous gel overlying the gastrointestinal mucosa that provides a physical barrier against various noxious agents. May inhibit the growth of calcium oxalate crystals in urine.
Synonyms: hP1.A; BCEI; PS2; D21S21; HPS2; pNR-2
Tractability: Antibody: UniProt places it where antibodies can reach, with high confidence; its Gene Ontology location is reachable by antibodies, with high confidence; UniProt predicts a signal peptide or a membrane-spanning region.
Gene: Protein-coding gene on chromosome 21 (42,362,282 to 42,366,535, reverse strand). Ensembl gene ENSG00000160182.
Subcellular location: Secreted
Pathways (Reactome):
Signal Transduction: Estrogen-dependent gene expression
Gene Ontology:
Molecular function: protein binding
Biological process: carbohydrate metabolic process; maintenance of gastrointestinal epithelium; response to immobilization stress; response to iron ion; response to peptide hormone
Cellular component: extracellular region
Genetic constraint (gnomAD): Loss-of-function variants: 8 observed, 8.2 expected, observed/expected ratio (o/e) 0.98, 90% interval 0.57 to 1.69. That is too few expected variants to judge how well the gene tolerates losing a copy. Missense variants: 120 observed, 113.9 expected, observed/expected ratio (o/e) 1.05, 90% interval 0.91 to 1.23. Synonymous variants: 47 observed, 46.3 expected, observed/expected ratio (o/e) 1.01, 90% interval 0.8 to 1.29.
Homologues: Orthologues: chimpanzee TFF1 (98% identical), macaque TFF1 (83% identical), dog TFF1 (68% identical), mouse Tff1 (64% identical), rat Tff1 (63% identical), pig TFF1 (54% identical), rabbit TFF1 (52% identical), tropical clawed frog tff3.8 (37% identical), tropical clawed frog tff3 (32% identical). Paralogues in human: TFF2 (42% identical), TFF3 (39% identical).
Diseases named in the same sentence as TFF1 in open-access papers:
TFF1 is named in the same sentence as 136 diseases in open-access papers, as found by Europe PMC text mining. Sharing a sentence is not in itself a finding about the gene and the disease. The quoted sentences say what the papers report.
breast carcinoma (124 papers, 2005 to 2026). "Enhanced KRT16 expression is significantly correlated with lower overall survival in metastatic breast cancer patients, while TFF1 is closely associated with bone metastasis in estrogen receptor (ER) + breast cancer." (PMID 38254021, 2024). "Much less is known about the biological role of TFF1, but it can serve as diagnostic and prognostic biomarker for breast cancer." (PMID 39583845, 2024). "For breast cancer, gastric adenocarcinoma and pancreatic ampullary adenocarcinoma studies have found associations between high TFF1 expression levels and both favorable and unfavorable tumor features." (PMID 39410561, 2024). "In 2021, a study on the role of TFF1 in the risk of breast cancer metastasising to bone was published." (PMID 37958607, 2023). "Significantly, we revealed that TFF1 expression was positively associated with circ‐TFF1 level in breast cancer tissues." (PMID 31961997, 2020). "The proto-oncogene products, c-myc, GREB1, and TFF1 have been implicated in the cellular proliferation, metastasis, and migration of breast cancer cells." (PMID 33177647, 2020). "Circ‐TFF1 and TFF1 were both upregulated and positively associated with each other in breast cancer." (PMID 31961997, 2020). "Normal mammary tissue expresses little or no TFF1 protein expression in normal breast ducts, and TFF1 expression is increased and positively associated with ER-positive tumors in breast cancer." (PMID 24959251, 2014). "TFF1, encoding a secretory protein with proinvasive and angiogenic effects, has an elevated expression in estrogen receptor α positive (ER+) breast cancers." (PMID 23675462, 2013). "Among the other genes in the list, NAT1, DNALI1, SCUBE2, and TFF1 have been implicated in breast cancer." (PMID 23365541, 2012). "However, high expression of TFF1 was shown to be associated with the estrogen status of patients and was found mainly in bone metastases from breast cancer." (PMID 38887221, 2024). "Besides that, TFF1 expression was demonstrated to be associated significantly with bone relapse of breast cancer patients, with the highest‐ranking gene in bone metastatic breast tumors." (PMID 38193110, 2024). "In BC, although the serum and tissue levels of TFF1 are typically overexpressed, many clinical studies have also reported that TFF1 deficiency increases tumorigenicity of human breast cancer cells, and TFF1 expression in BC has an effect on good clinical outcomes for patients." (PMID 36755810, 2023). "TFF1 has been associated with enhancing the oncogenicity of mammary carcinoma cells." (PMID 35298474, 2022). "Expression of TFF1 in breast cancer may be associated with a poor outcome based upon breast cancer cell lines and a mouse model." (PMID 26510686, 2015). "Expression of TFF1, a gene encoding a small secretory peptide implicated in preserving mucosa in the intestinal track, is associated with promoter hypomethylation in cultured cells and in breast cancers." (PMID 26510686, 2015). "In addition, TFF1 mRNA levels and associated gene expression patterns were analyzed using publicly available datasets, including the Molecular Taxonomy of Breast Cancer International Consortium (METABRIC, n = 939) and the Cancer Cell Line Encyclopedia (n = 47)." (PMID 41547953, 2026). "We speculated that serum TFF1 could be a diagnostic biomarker of breast cancer." (PMID 35692369, 2022). "We assessed TFF1 protein expression by immunohistochemistry (IHC) in biopsies from patients with primary breast cancer diagnosed before age 50 and their paired axillary lymph node (LN) metastases within our in-house Bergen Young BC Cohort (n = 319)." (PMID 41547953, 2026). "Here, we present a protocol that integrates fixed-cell smFISH and live-cell single-molecule imaging to analyze estrogen-responsive transcriptional bursting of the TFF1 gene in human breast cancer cell lines." (PMID 42146558, 2026).
breast carcinoma (continued). "The luminal breast cancer cell line MCF7 was shown to be a good model for this variability as TFF1 transcription in response to estrogen (17β-estradiol, E2) stimulation is marked by a pronounced heterogeneity." (PMID 41000645, 2025). "TFF1 expression is thought to protect against breast cancer and high expression levels in breast cancer patients are associated with a good prognosis." (PMID 39583845, 2024). "For instance, trefoil factor family 1 (TFF1) is a peptide that was found to inhibit gastric cancer but promote the progression of breast cancer." (PMID 38887221, 2024). "In contrast, we previously demonstrated a significant reduction of proliferation in ERα-positive MCF7 human breast cancer cells after siRNA-mediated knockdown of TFF1, similar to the effect of ERα, GREB1 or PR knockdown." (PMID 39583845, 2024). "Some of the properties of TFF1 include inhibition of cell growth, colony formation, and migration and invasion of breast cancer cells in vitro." (PMID 36836779, 2023). "TFF1 has previously been identified as a functional biomarker in various other types of tumors, such as breast cancer, esophageal squamous cell carcinoma, and gastric cancer." (PMID 37835522, 2023). "TFF1 was identified as a strictly correlated primary tumour marker of bone metastases for ER+ breast cancer." (PMID 37958607, 2023). "TFF1 is already described as a functional biomarker in several other tumor entities, e.g., breast cancer, esophageal squamous cell carcinoma, and gastric cancer." (PMID 35158945, 2022). "Combining dynamic enhanced MRI with serum CA15-3, CYFRA21-1, and TFF1 has good efficacy in diagnosing breast cancer, which can be applied in clinical diagnosis of breast cancer." (PMID 35392152, 2022). "The study found that combining dynamic enhanced MRI with serum CA15-3, CYFRA21-1, and TFF1 has a good efficacy in diagnosing breast cancer, which can be applied in the clinical diagnosis of breast cancer." (PMID 35392152, 2022). "The TFF1 protein was reported to stimulate breast cancer cell migration and to exert apoptosis-protecting effects in doxorubicin-treated cells." (PMID 36358871, 2022). "The CA15-3, CYFRA21-1, and TFF1 levels were significantly higher in the breast cancer group than in the benign group and control group (P < 0.05)." (PMID 35392152, 2022). "Hsa-circ-0061825 (circ-TFF1) contributes to BC via targeting miR-326/TFF1, and circNOT2 can prevent breast cancer invasion, migration and EMT by regulating twist family BHLH transcription factor via targeting miR-409-3p/Twist1." (PMID 35806027, 2022). "Previous research found that the down-regulation of circTFF1 can inhibit the occurrence of breast cancer by sponging miR-326 and increasing the expression level of TFF1." (PMID 36006268, 2022). "Apart from PGR, other estrogen target genes have been considered for their association with ER status and/or prediction of response to hormonal therapies, including pS2/TFF1 and Growth Regulation by Estrogen in Breast cancer 1 (GREB1)." (PMID 36358871, 2022). "In breast cancer, a correlation of high TFF1 expression in blood samples of patients with metastatic disease compared to those without metastatic disease has been demonstrated." (PMID 35158945, 2022). "By using GSE65194, we performed ROC curve analysis to access the diagnostic value of four DEmRNAs (TFF1, COL10A1, LEP, and PLIN1) and two DEmRNAs (PGM5-AS1 and TRHDE-AD1) in luminal A breast cancer." (PMID 35692369, 2022). "Five genes demonstrated significantly higher expression in breast cancer bone metastasis (BCBM): TFF1, TFF3, AGR2, NAT1, and CR1P1." (PMID 35804819, 2022). "Breast cancer cells overexpressing miR-205 reduced leptin-mediated Med1, TFF1, and CATD overexpression whereas expression of miR-205-inhibitor potentiated the effect of leptin on Med1 expression." (PMID 34389732, 2021).
breast carcinoma (continued). "The research was the first to report the tumour‐promoting role of circ‐TFF1 in breast cancer, affecting cell proliferation, apoptosis, migration and invasion, and EMT process." (PMID 31961997, 2020). "Circ‐TFF1 acted as a ceRNA of TFF1 by sponging miR‐326, and its contribution to breast cancer progression was mediated by miR‐326/TFF1 axis." (PMID 31961997, 2020). "In the current study, we identified ten significantly variable circRNAs in breast cancer and paired normal tissues, and selected hsa_circ_0061825 (circ‐TFF1) due to the highest expression in breast cancer tissues." (PMID 31961997, 2020). "In subsequent, rescue experiments were performed to verify the role of circ‐TFF1/miR‐326/TFF1 in breast cancer." (PMID 31961997, 2020). "Circ‐TFF1 is a facilitator in breast cancer relying on TFF1 by absorbing miR‐326, providing a novel promising target for BC treatment." (PMID 31961997, 2020). "By the large, these findings clarified that knockdown of circ‐TFF1 caused the obstruction of cell migration, invasion and EMT in breast cancer." (PMID 31961997, 2020). "In a word, these results validated that suppression of circ‐TFF1 hindered breast cancer cell growth in vivo." (PMID 31961997, 2020). "In summary, this investigation proved that circ‐TFF1, which derived from the host gene TFF1, elicited an oncogenic function in breast cancer by freeing TFF1 from miR‐326‐induced silence." (PMID 31961997, 2020). "Then, we measured the expression of circ‐TFF1 in breast cancer cells and verified that circ‐TFF1 level in breast cancer cells was higher than in normal cells." (PMID 31961997, 2020). "H2A.Z is also found to be deposited within the promoter of TFF1 (Trefoil factor 1), an ER-α positive breast cancer tumour marker." (PMID 32257110, 2020). "On the whole, circ‐TFF1 knockdown inhibited cell proliferation but encouraged apoptosis in breast cancer." (PMID 31961997, 2020). "Namely, we concluded that circ‐TFF1 executed its function in the progression of breast cancer by modulation of miR‐326/TFF1 axis." (PMID 31961997, 2020). "ERRα up-regulates not only the recruitment to breast cancer biomarker gene TFF1 promoter, but also its expression upon breast cancer cell treatment with epidermal growth factor (EGF)." (PMID 31894856, 2020). "By analysis of TCGA data, it was found that TFF1 was intensively expressed in tumours from breast cancer patients compared to the normal tissues, while this result was also confirmed in the collected clinical samples in this study." (PMID 31961997, 2020). "Taken together, the upregulated circ‐TFF1 and its host gene TFF1 were positively correlated in their expression in breast cancer tissues." (PMID 31961997, 2020). "In the present study, we uncovered a novel circRNA called hsa_circ_0061825 (circ‐TFF1) as a contributor in breast cancer progression." (PMID 31961997, 2020). "The link between the modulatory mechanism of circ‐TFF1‐miR‐326‐TFF1 axis and cellular activities in breast cancer is revealed here for the first time, and our findings will offer a novel insight into the therapy of breast cancer patients." (PMID 31961997, 2020). "Promoter region of a breast cancer marker gene and an inferior prognostic factor, trefoil factor 1 (TFF1) is occupied by MSK1 and decorated with H3S10ph." (PMID 33054831, 2020). "Knockdown of circ‐TFF1 hindered breast cancer cell proliferation, migration, invasion and EMT in vitro and controlled tumour growth in vivo." (PMID 31961997, 2020). "In vitro and in vivo experiments were conducted to assess the function of circ‐TFF1 in biological processes in breast cancer cells." (PMID 31961997, 2020). "It has been reported that TFF1 mRNA level is higher in blood and in ER positive primary tumor in breast cancer patients with metastatic disease compared with the patients without metastasis." (PMID 30781353, 2019).
breast carcinoma (continued). "Among the listed genes, BIRC5, SEC14L2, Thymidine kinase (TK1), ZNF385B, CLIC6, ELOVL1, CHAF1B and TFF1 have been reported to have a role in early detection of cancers, tumor progression and metastasis in most of cancer types including breast cancer." (PMID 31703592, 2019). "Recently, MSK1 and MSK2 were also found to be involved in the regulation of phorbol ester-induced activation of trefoil factor 1 (TFF1), a breast cancer marker, in MCF-7 cells." (PMID 29327245, 2018). "TFF1 is known to play a role in breast cancer development and bone metastasis, has also been suggested as a poor prognostic indicator associated with lymph node metastasis in pancreatic cancer." (PMID 29682207, 2018). "Our new model reconciles the conflicting studies into the ER at the TFF1 promoter and provides a detailed understanding in the context of the ER’s role as both the driver and therapeutic target of breast cancer." (PMID 30457555, 2018). "The TFF1 gene was negatively correlated with the expression level for miR-200b in both breast cancer subtypes, meanwhile RARA gene was negatively correlated only in TNBC." (PMID 30342533, 2018). "As regards TFF1 mRNA concentration in serum samples of PR + breast cancer patients, we found that only 4 cases with high TFF1 were PR+ (44.4%)." (PMID 29977293, 2018). "Serum TFF2 levels in breast cancer patients were significantly lower than in healthy individuals (TFF1: 1.48 ± 1.43 ng/ml, P = 0.0004, TFF2: 3.90 ± 1.90 ng/ml, P = 0.0003, TFF3: 6.96 ± 1.45 ng/ml, P = 0.0313)." (PMID 28687783, 2017). "Among the 46 breast cancers analyzed, TFF1 staining was graded as 3+ in 6 patients (13%), 2+ in 20 patients (43.5%), 1+ in 11 patients (23.9%), and no staining in 9 patients (19.6%)." (PMID 28687783, 2017). "In our cohort, TFF1 was positive in normal epithelial tissue surrounding breast cancer in 8.7% of patients and TFF3 was positive in normal epithelial tissue surrounding breast cancer in 21.7% of patients." (PMID 28687783, 2017). "Although stimulation of MCF7 breast cancer cells with E2 radically increased ERα occupancy on TFF1, L-ChIP yielded much higher detection sensitivities (about 100%) than X-ChIP." (PMID 28916762, 2017). "For example, TFF1 gene is up-regulated in the whole breast cancer cohort but down-regulated in the basal-like subtype." (PMID 27633916, 2016). "We can see that TFF1 gene tend to be high-expressed in breast cancer according to differential expression analysis, but it is significantly low-expressed when restricted to basal-like subtype tumors." (PMID 27633916, 2016). "A similar effect of higher concentrations of TFF1 has been observed for TFF1 simulation of mammary carcinoma cell migration." (PMID 26559818, 2015). "Cancer-associated hypomethylation of TFF1 and MAGEA1 was also observed by Illumina HumanMethylation450 analysis of DNA methylation in the TCGA database for breast cancer and paired normal samples." (PMID 26510686, 2015). "MSK1 is responsible for histone H3 phosphorylation of estrogen-responsive Trefoil Factor-1 (TFF-1) promoter in breast cancer MCF-7 cells." (PMID 25958199, 2015). "TFF1 is a peptide that is expressed at low levels in normal breast tissue, but at high levels in ERα+ breast carcinomas in response to E2." (PMID 25070479, 2014). "TFF1 expression is known to be upregulated by E2 and has been shown to be an inhibitor of breast cancer metastasis in an animal model." (PMID 25298020, 2014). "TFF1 protein is a marker for ER+, well-differentiated, low-grade breast cancers (about 65% of all breast cancers)." (PMID 23675462, 2013). "Here, we demonstrate that both MSK1 and MSK2, regulate the phorbol ester 12-O-tetradecanoylphorbol-13-acetate induced expression of the breast cancer marker gene, trefoil factor 1 (TFF1), by phosphorylating H3S10 at its 5′ regulatory regions." (PMID 23675462, 2013).